NCAPH2 (non-SMC condensin II complex subunit H2)
Description:
Regulatory subunit of the condensin-2 complex, a complex that seems to provide chromosomes with an additional level of organization and rigidity and in establishing mitotic chromosome architecture. May promote the resolution of double-strand DNA catenanes (intertwines) between sister chromatids. Condensin-mediated compaction likely increases tension in catenated sister chromatids, providing directionality for type II topoisomerase-mediated strand exchanges toward chromatid decatenation. Required for decatenation of chromatin bridges at anaphase. Early in neurogenesis, may play an essential role to ensure accurate mitotic chromosome condensation in neuron stem cells, ultimately affecting neuron pool and cortex size (By similarity). Seems to have lineage-specific role in T-cell development.
Synonyms: hCAP-H2; CAPH2; 384D8-2; CAP-H2
Tractability: PROTAC: ubiquitination databases record sites on it.
Gene: Protein-coding gene on chromosome 22 (50,508,213 to 50,524,780, forward strand). Ensembl gene ENSG00000025770.
Subcellular location: Nucleus; Chromosome
Subcellular location (Human Protein Atlas): Nucleoplasm; Cell Junctions; Cytokinetic bridge
Pathways (Reactome):
Cell Cycle: Condensation of Prophase Chromosomes
Gene Ontology:
Molecular function: protein binding; chromatin binding
Biological process: meiotic chromosome condensation; mitotic chromosome condensation; mitotic sister chromatid separation; chromosome condensation
Cellular component: chromosome; membrane; nucleoplasm; nucleus; condensin complex
Genetic constraint (gnomAD): Loss-of-function variants: 56 observed, 88.34 expected, observed/expected ratio (o/e) 0.63, 90% interval 0.51 to 0.79. The synonymous counts are far from expectation, so gnomAD's model fits this gene poorly and the ratio says little. Missense variants: 794 observed, 778.81 expected, observed/expected ratio (o/e) 1.02, 90% interval 0.96 to 1.08. Synonymous variants: 378 observed, 309.25 expected, observed/expected ratio (o/e) 1.22, 90% interval 1.12 to 1.33.
Homologues: Orthologues: chimpanzee NCAPH2 (99% identical), macaque NCAPH2 (95% identical), guinea pig NCAPH2 (83% identical), rat Ncaph2 (81% identical), pig NCAPH2 (81% identical), mouse Ncaph2 (80% identical), dog NCAPH2 (79% identical), rabbit NCAPH2 (65% identical), tropical clawed frog ncaph2 (53% identical), zebrafish ncaph2 (38% identical), Caenorhabditis elegans kle-2 (22% identical).
Diseases named in the same sentence as NCAPH2 in open-access papers:
NCAPH2 is named in the same sentence as 14 diseases in open-access papers, as found by Europe PMC text mining. Sharing a sentence is not in itself a finding about the gene and the disease. The quoted sentences say what the papers report.
Alzheimer disease (3 papers, 2016 to 2023). A progressive, neurodegenerative disease characterized by loss of function and death of nerve cells in several areas of the brain leading to loss of cognitive function such as memory and language. "Abnormal methylation of NCAPH2 in the blood of patients with subjective cognitive decline may be a biomarker for early screening of Alzheimer’s disease, but no related research has mentioned that NCAPH2 was related to cancer prognosis." (PMID 37192046, 2023).
Cirrhosis (1 paper, 2023). A chronic disorder of the liver in which liver tissue becomes scarred and is partially replaced by regenerative nodules and fibrotic tissue resulting in loss of liver function. "A total of 97 HCC patients with cirrhosis were selected from TCGA, and 5 genes (ADH1C, ACSL4, GPD2, ME1, NCAPH2) were selected to construct a FAM-related prognosis signature via Lasso–Cox regression using this cohort." (PMID 36671526, 2023).
Cognitive impairment (1 paper, 2021). Abnormal cognition is characterized by deficits in thinking, reasoning, or remembering. "Thus, a dissociation between NCAPH2 hypomethylation and the markers of neurodegeneration, including hippocampal atrophy and cognitive impairment, was observed in the late stage of AD." (PMID 33603659, 2021). "A possible explanation for this difference in outcome could be that NCAPH2 methylation has reached a plateau phase in the early stage of AD, leading to little meaningful variance in methylation levels between patients with cognitive impairment." (PMID 33603659, 2021). "Our results indicated that the NCAPH2 methylation levels decreased during the SCD stage of the disease and reached a plateau at the cognitive impairment stage, suggesting that altered blood NCAPH2 methylation might be an early feature of AD pathology." (PMID 33603659, 2021).
hippocampal atrophy (1 paper, 2021). "We hypothesize that dysregulation of NCAPH2 methylation may lead to an abnormal immune response and finally to hippocampal atrophy." (PMID 33603659, 2021). "This is not consistent with observations from the previous research, showing a correlation between NCAPH2/LMF2 methylation and hippocampal atrophy in AD." (PMID 33603659, 2021).
Obesity (1 paper, 2017). Accumulation of substantial excess body fat. "Specifically, the methylation levels of FGFRL1, NCAPH2, PNKD and SMAD3 exhibited excellent and statistically significant efficiencies in the discrimination of obesity from non-obesity status (AUC > 0.80; p < 0.05) and a great correlation between both tissues." (PMID 28211912, 2017). "Relevantly, the areas under the ROC curves (AUCs) for FGFRL1, NCAPH2, PNKD, and SMAD3 evidenced excellent and statistically significant efficiencies in discriminating obesity from non-obesity in both the subcutaneous adipose tissue and leukocytes." (PMID 28211912, 2017).
ovarian carcinoma (1 paper, 2023). A malignant neoplasm originating from the surface ovarian epithelium. "Interestingly, none of the four top genes WBP1L, ASAP3, CNNM2, and NCAPH2 was correlated with ovarian cancer pathogenesis previously." (PMID 36856946, 2023).
round cell liposarcoma (1 paper, 2023). A poorly differentiated liposarcoma, characterized by the presence of solid sheets of primitive round mesenchymal cells and the absence of myxoid stroma. "NCAPH2 was upregulated in Round Cell Liposarcoma with a fold change of 2.013 (p = 0.002)." (PMID 37192046, 2023).
sarcoma (1 paper, 2023). A usually aggressive malignant neoplasm of the soft tissue or bone. "In our research, we also found that the overexpression of NCAPH2 had statistical significance in correlation with low RFS of sarcoma patients." (PMID 37192046, 2023). "The high expression of NCAPD2, NCAPG, NCAPH, NCAPD3, and NCAPH2 were all correlated with the relapse-free survival of sarcoma patients, HR = 2.76 (p = 3.3e-05), 2.72 (p = 0.0012), 2.71 (p = 0.0026), 1.87 (p = 0.01) and 2.08 (p = 0.029) respectively." (PMID 37192046, 2023). "Six members of the NCAPs family, including NCAPD2, NCAPG, NCAPH, NCAPD3, NCAPG2, and NCAPH2, have been found in different types of sarcomas." (PMID 37192046, 2023). "In this study, ONCOMINE, GEPIA, Kaplan-Meier plotter, DAVID (KEGG and GO analysis), and TIMER datasets were utilized to study the high expression, prognosis analysis, signal pathway and immune correlation of NCAPD2, NCAPG, NCAPH, NCAPD3, NCAPG2, and NCAPH2 in sarcoma for the first time." (PMID 37192046, 2023). "The high expression of NCAPH2 was correlated with poor overall survival of sarcoma patients but had no statistical significance (p > 0.05)." (PMID 37192046, 2023). "Up to now, NCAPD2, NCAPG, NCAPH, NCAPD3, NCAPG2, and NCAPH2 have not been mentioned in sarcoma, except NCAPG mentioned in Ewing sarcoma." (PMID 37192046, 2023). "NCAPD3 and NCAPH2 were also upregulated in sarcoma samples but with no significance." (PMID 37192046, 2023).
cancer (7 papers, 2017 to 2025). A tumor composed of atypical neoplastic, often pleomorphic cells that invade other tissues. "Using publicly available patient derived datasets obtained from TCGA, we determined that all eight condensin genes (SMC2, SMC4, NCAPD2, NCAPD3, NCAPG, NCAPG2, NCAPH, and NCAPH2) are frequently altered in at least 12 common cancer types." (PMID 31357676, 2019). "Finally, a recent HotNet2 Pan-Cancer analysis suggested that multiple cancers harbor rare mutations in SMC2, SMC4, NCAPD2, NCAPD3, NCAPH2 and NCAPG2, supporting a tumor-suppressor role for condensin proteins." (PMID 36169232, 2022).
tumor (4 papers, 2010 to 2024). "Herein, we confirmed the transcription levels of non-SMC subunit NCAPD3, NCAPH2, and NCAPD2 exhibited an increase in tumor tissues compared to adjacent nontumor tissues by RNA-seq analysis, among which only NCAPD3 showed a statistically significant change." (PMID 38561330, 2024).
NCAPH2 also shares sentences with these, for which no sentence is quoted: cognitive decline (2 papers); breast carcinoma (1); cervical cancer (1); laryngeal carcinoma (1).